ADARB2 (adenosine deaminase RNA specific B2 (inactive))
Description:
Single- and double-stranded RNA-binding protein that interferes with the RNA editing activities of ADAR/ADAR1 and ADARB1/ADAR2. Likely competes with these proteins for target binding, repressing RNA editing across the transcriptome. Additionally, it binds and stabilizes specific mRNAs and regulates the expression of proteins such as MAVS, DUSP1, and EGR1, independently of RNA editing mechanisms.
Synonyms: ADAR3; RED2; hRED2
Tractability: PROTAC: ubiquitination databases record sites on it; its protein half-life has been measured.
Gene: Protein-coding gene on chromosome 10 (1,177,313 to 1,737,525, reverse strand). Ensembl gene ENSG00000185736.
Subcellular location: Nucleus
Subcellular location (Human Protein Atlas): Nucleoplasm; Cytosol; Mitochondria
Gene Ontology:
Molecular function: double-stranded RNA adenosine deaminase activity; mRNA binding; RNA binding; RNA sequestering activity; double-stranded RNA binding; adenosine deaminase activity
Biological process: 3'-UTR-mediated mRNA stabilization; negative regulation of mRNA modification; adenosine to inosine editing; RNA processing
Cellular component: nucleoplasm; nucleus; cytoplasm; nucleolus
Genetic constraint (gnomAD): Loss-of-function variants: 24 observed, 49.56 expected, observed/expected ratio (o/e) 0.48, 90% interval 0.35 to 0.68. The synonymous counts are far from expectation, so gnomAD's model fits this gene poorly and the ratio says little. Missense variants: 1,070 observed, 940.19 expected, observed/expected ratio (o/e) 1.14, 90% interval 1.08 to 1.2. Synonymous variants: 572 observed, 445 expected, observed/expected ratio (o/e) 1.29, 90% interval 1.2 to 1.38.
Homologues: Orthologues: macaque ADARB2 (99% identical), rabbit ADARB2 (86% identical), guinea pig ADARB2 (85% identical), chimpanzee ADARB2 (85% identical), mouse Adarb2 (84% identical), rat Adarb2 (83% identical), pig ADARB2 (82% identical), dog ADARB2 (78% identical), tropical clawed frog adarb2 (72% identical), zebrafish adarb2 (66% identical), Drosophila melanogaster loqs (12% identical), Drosophila melanogaster Zn72D (11% identical), and 3 more. Paralogues in human: ADARB1 (50% identical), ADAR (31% identical), ADAD1 (19% identical), ADAD2 (19% identical), ADAT1 (17% identical), ZFR2 (13% identical), ZFR (12% identical), STAU2 (12% identical), ILF3 (12% identical), TARBP2 (11% identical), STRBP (11% identical), STAU1 (10% identical), and 2 more.
Diseases named in the same sentence as ADARB2 in open-access papers:
ADARB2 is named in the same sentence as 55 diseases in open-access papers, as found by Europe PMC text mining. Sharing a sentence is not in itself a finding about the gene and the disease. The quoted sentences say what the papers report.
glioblastoma (15 papers, 2013 to 2025). The most malignant astrocytic tumor (WHO grade IV). "ADARB2 (ADAR3) mRNA was decreased in glioblastoma multiforme, suggesting that reduced A-to-I editing is involved in brain carcinogenesis." (PMID 23737728, 2013). "Reduced RNA expression of ADARB2 was found in low-grade astrocytomas, anaplastic astrocytomas, glioblastomas, and oligodendrogliomas compared to normal brain tissue, with the lowest expression found in glioblastomas." (PMID 40358182, 2025). "Interestingly, a similar epigenetic signature for AJAP1, ADARB2 and PTPRN2 has been previously reported in glioblastoma." (PMID 28514750, 2017).
glioma (13 papers, 2018 to 2025). A benign or malignant brain and spinal cord tumor that arises from glial cells (astrocytes, oligodendrocytes, ependymal cells). "Interestingly, we found reduced levels of ADARB1 and ADARB2 in glioma samples, indicating that these two ADAR family enzymes may play an important role in A-to-I RNA editing events in glioma." (PMID 33062411, 2020). "ADARB2 (Adenosine Deaminase Rna Specific B2), also known as ADAR3, known to antagonize ADAR1 and ADAR2 by competing with them also showed some decrease in high-grade gliomas." (PMID 35042936, 2022). "The data showed that ADARB2 and EIF4E1B had lower expression levels in glioma grade IV than II samples (both p < 0.001)." (PMID 33634155, 2021). "Our study revealed RNA editing levels to be higher in control brain samples and it is significantly reduced in glioma samples which correlate with the RNA expression levels of the ADAR enzymes ADARB1 and ADARB2." (PMID 33062411, 2020). "From this, we can say that overall RNA editing events occur at a reduced frequency in glioma compared to normal and ADAR family enzymes ADARB1 and ADARB2 may be responsible for this decreased editing." (PMID 33062411, 2020).
brain tumors (6 papers, 2011 to 2022). "The ADARB2 gene (RNA-specific adenosine deaminases, B2) is associated with brain tumors and a single nucleotide polymorphism (SNP) in ADARB2 is associated with metabolic disorders." (PMID 26310571, 2015). "All 3 editing mediating enzymes, ADAR1 (ADAR), ADAR2 (ADARB1), and ADAR3 (ADARB2), is downregulated in brain tumors and ADARB2 is also negatively correlated with GBM grades." (PMID 32244981, 2020).
Alzheimer disease (4 papers, 2019 to 2024). A progressive, neurodegenerative disease characterized by loss of function and death of nerve cells in several areas of the brain leading to loss of cognitive function such as memory and language. "Other variants in ADARB2 have been associated with several brain disorders, including amyotrophic lateral sclerosis and Alzheimer’s disease, longevity and different types of cancers." (PMID 38802570, 2024). "Smoking history was included in the linear mixed effects model as a fixed effect, and interaction term, to determine whether this adjustment attenuates association of the ADARB2 DNA methylation mark with Alzheimer’s disease." (PMID 31477183, 2019).
Anxiety (4 papers, 2018 to 2022). Intense feelings of nervousness, tension, or panic often arise in response to interpersonal stresses. "Recent studies on the catalytically inactive isoform ADAR3 has revealed knockout of exon 3 of the Adarb2 gene, which encodes its two double stranded RNA binding domains, results in altered behavior related to anxiety and learning in mice." (PMID 32597966, 2020). "We also demonstrate that mice lacking exon 3 of Adarb2 (referred to herein as Adar3exon3), containing the double stranded RNA binding domains, display increased anxiety levels and impaired short and long-term hippocampus-dependent memory formation." (PMID 29719497, 2018).
brain cancer (3 papers, 2018 to 2025). A primary or metastatic malignant neoplasm affecting the brain. "ADARB2 is also thought to effect stemness and was found to be a possible tumor-suppressor in papillary thyroid cancer and brain cancers." (PMID 40358182, 2025).
mild cognitive impairment (3 papers, 2019 to 2024). "Consistently, a variant in ADARB2 gene has been associated with accelerated cognitive decline after conversion from mild cognitive impairment (MCI) to AD." (PMID 31477183, 2019).
depression (2 papers, 2022 to 2023). "Further supporting the role of adenosine in stress-induced depression, we also identified three adenosine deaminases (Ada, Adarb1, and Adarb2) in our CSDS and ASDS-CSDS-LSDS analyses." (PMID 37228107, 2023).
migraine (2 papers, 2015 to 2024). "SNPs in the ADARB2 gene were previously found to be positively associated with migraine in a pedigree-based genome wide association study using the genetic isolate of Norfolk Island, Australia." (PMID 25916332, 2015). "The aim of this study was to determine if SNPs in the ADARB1 and ADARB2 genes contribute to migraine susceptibility in an Australian case–control cohort." (PMID 25916332, 2015). "In this study we tested four SNPs in the ADARB1 gene and eight SNPs in the ADARB2 for association with migraine susceptibility." (PMID 25916332, 2015). "We previously identified four SNPs forming a 22 kb haplotype block in ADARB2 that were positively associated with migraine susceptibility in a pedigree-based GWAS (pGWAS) of the population of Norfolk Island." (PMID 25916332, 2015). "This study was undertaken to follow up findings from a pGWAS we previously conducted in the Norfolk Island pedigree which implicated four SNPs in the RNA editing gene ADARB2 in migraine, based on statistical significance." (PMID 25916332, 2015). "ADARB2 SNPs have been associated with migraine in one study on a small isolated island population." (PMID 38802570, 2024). "The aim of this study was to investigate single nucleotide polymorphisms (SNPs) in the adenosine deaminase, RNA-specific, B1 (ADARB1) and adenosine deaminase, RNA specific, B2 (ADARB2) genes in an Australian case–control Caucasian population for association with migraine." (PMID 25916332, 2015). "Collectively, association of variants in these neurotransmitter-related genes ADARB2; GRM7; HTR7 connected by a common neurological pathway supports current theories of a perturbed serotonin and glutamate mechanism in migraine and in the Norfolk pedigree." (PMID 25916332, 2015). "In this study we genotyped four SNPs in ADARB1 and nine SNPs in ADARB2 using either TaqMan or Sequenom assays to investigate their involvement in migraine." (PMID 25916332, 2015). "Considering the association of ADARB2 with migraine in the Norfolk Island pGWAS we decided to investigate SNPs in this gene, as well as another RNA editing gene, ADARB1, in an Australian migraine case–control population." (PMID 25916332, 2015). "In addition to ADARB2 SNPs, the Norfolk Island pGWAS also found two SNPs in the glutamate receptor, metabotropic 7 (GRM7) gene and one SNP in the 5-hydroxytryptamine serotonin receptor 7 adenylate cyclase-coupled (HTR7) gene to be associated with migraine." (PMID 25916332, 2015). "Although we were unable to replicate our findings from the Norfolk Island population implicating four ADARB2 SNPs in migraine in an Australian Caucasian population, it does not exclude a role for ADARB2 in migraine in the unique Norfolk Island population isolate." (PMID 25916332, 2015).
autoimmune disease (1 paper, 2023). A disorder resulting from loss of function or tissue destruction of an organ or multiple organs, arising from humoral or cellular immune responses of the individual to their own tissue constituents. "Altered DNA methylation of genes, such as, PON1, ADARB2, USP16, UHMK1, and DISC1, was previously reported to be related to cancer or autoimmune diseases." (PMID 37744384, 2023).
head and neck cancer (1 paper, 2025). A primary or metastatic malignant neoplasm affecting the head and neck. "The biological relevance of these findings is difficult to interpret, particularly given the absence of published data on ADARB2 expression in head and neck cancer cell lines." (PMID 41300768, 2025).
Headache (1 paper, 2024). Cephalgia, or pain sensed in various parts of the head, not confined to the area of distribution of any nerve. "A genome-wide association study in a cohort of 63,992 Danish blood donors identified an association between complete freedom from headache and a locus in the ADARB2 gene." (PMID 38802570, 2024). "In conclusion, we show that complete freedom from headache has a genetic component, and we suggest that ADARB2 is involved in complete freedom from headache." (PMID 38802570, 2024).
headache disorder (1 paper, 2024). Various conditions with the symptom of headache. "Our results suggest the involvement of ADARB2, a locus specific to CFH and independent of headache disorders." (PMID 38802570, 2024).
hearing loss (1 paper, 2021). "We observed that several SNPs in SCARNA16, IQGAP2, PTPRK, GLI3, ADARB2 and NDUFV2, which have been reported to be significantly associated with several other types of hearing loss, were also significantly associated with NIHL in this study (all P values ≤ 0.05)." (PMID 33242228, 2021).
Moyamoya disease (1 paper, 2024). Moyamoya disease (MMD) is a rare intracranial arteriopathy involving progressive stenosis of the cerebral vasculature located at the base of the brain causing transient ischemic attacks or strokes. "Next, the expression levels of five key genes were found to correlate with the expression levels of several moyamoya disease-related genes, with H19 positively correlating with ADARB2 (Pearson r = 0.628) and STK3 negatively correlating with ISG15 (Pearson r = − 0.556)." (PMID 38704490, 2024).
oral cavity tumors (1 paper, 2025). "In the TCGA dataset, the highest ADARB2 expression was observed in pharyngeal tumors and the lowest in oral cavity tumors." (PMID 41300768, 2025).
oropharyngeal tumors (1 paper, 2025). "The highest ADARB2 expression was detected in oropharyngeal tumors." (PMID 41300768, 2025).
pancreatic ductal adenocarcinoma (1 paper, 2019). An infiltrating adenocarcinoma that arises from the epithelial cells of the pancreas. "Among the fifteen RFS-related lncRNA, ADARB2.AS1, and LINC02471 have been previously reported to be related with cancers, including breast cancer, pancreatic ductal adenocarcinoma and papillary thyroid carcinoma." (PMID 31767907, 2019).
pharyngeal tumors (1 paper, 2025). "Subsite analysis revealed high ADAR expression correlated with poor OS in pharyngeal tumors (p < 0.05), whereas high ADARB2 expression was linked to improved DFS (pa = 0.0023, pb = 0.0047)." (PMID 41300768, 2025).
prion disease (1 paper, 2020). A transmissible disease that is caused by a protein that is able to induce abnormal folding of normal cellular proteins, leading to characteristic spongiform brain changes, which are associated with neuronal loss without an inflammatory response. "The expression levels of the ADAR enzymes, Adar1 and Adarb2 did not change during prion disease progression, whereas Adarb1 was significantly downregulated at the terminal stage." (PMID 32598380, 2020).
teratoma (1 paper, 2024). A non-seminomatous germ cell tumor characterized by the presence of various tissues which correspond to the different germinal layers (endoderm, mesoderm, and ectoderm). "As expected, ADAR exhibited ubiquitous expression across all teratoma cell-types, while ADARB2 was neural-specific and ADARB1 was most highly expressed in neural tissues, and at lower levels elsewhere." (PMID 39537590, 2024). "Similar to week 10 teratomas, we observed ubiquitous expression of ADAR across all stages of teratoma development, while ADARB2 exhibited neural-specific expression, and ADARB1 showed strongest expression in neural tissues but also was expressed at low levels elsewhere." (PMID 39537590, 2024).
thyroid carcinoma (1 paper, 2021). "For instance, we failed to explore the role of the 5 feature genes (BMP8A, ADARB2, SALL3, PPBP, and SCN1A) in onset and progression of thyroid carcinoma by molecular experiments, cell experiments, or animal experiments." (PMID 34697553, 2021).
tumor (16 papers, 2011 to 2025). "While ADAR1 appears to act as an oncogenic driver through RNA-editing–dependent and independent mechanisms, ADARB2 in contrast emerges as a potential tumor suppressor, with its loss linked to enrichment of oncogenic pathways in our GSEA analyses." (PMID 41300768, 2025). "While ADAR1 and ADAR2 have been implicated in cancer biology across multiple tumor types, the role of ADARB2 remains poorly understood." (PMID 41300768, 2025). "In silico analyses of TCGA cohorts confirmed differential expression of all three ADAR family members, with ADAR (ADAR1) and ADARB1 (ADAR2) being significantly upregulated in tumor tissues, while ADARB2 (ADAR3) was markedly downregulated." (PMID 41300768, 2025). "In contrast, ADARB2 expression was predominantly reduced in cancers, with downregulation observed in approximately 75% of analyzed tumor types." (PMID 41300768, 2025). "Despite interpatient variability, statistical analysis revealed that only ADARB2 expression differed significantly between tumor and normal tissues (p = 0.044), with reduced levels in cancer samples." (PMID 41300768, 2025). "The gene body region of ADARB2 resulted extremely hypomethylated in HCC tumor compared to adjacent tissues." (PMID 28514750, 2017). "ADARB2 expression is significantly reduced in tumor tissues compared with adjacent normal mucosa." (PMID 41300768, 2025). "Similarly, the ADARB2 gene body is extremely hypomethylated in HCC tumor, relative to adjacent tissues." (PMID 37744384, 2023). "Moreover, low ADARB2 expression is associated with the enrichment of oncogenic pathways such as Wnt/β-catenin, Notch, Hedgehog, and TGF-β1 signaling, which may contribute to aggressive tumor behavior." (PMID 41300768, 2025). "In clinical samples collected from 10 patients with HNSCC, the expression of all analyzed genes (ADAR, ADARB1, and ADARB2) varied between tumor and adjacent non-cancerous tissues." (PMID 41300768, 2025). "Based on TCGA clustering data for ADAR, ADARB1, and ADARB2, fold changes in gene expression between tumor and matched non-cancerous tissues were calculated using median expression values." (PMID 41300768, 2025). "A gradual, though not statistically significant, decrease in ADARB2 expression was also noted with increasing tumor volume and higher histological grade." (PMID 41300768, 2025). "Notably, certain “writers” (such as ADARB2 and PCF11) with widespread frequency of CNV gain harbored decreased mRNA level in BCa compared to adjacent non-tumor tissues." (PMID 37124622, 2023). "The expression of ADARB2 was downregulated in all three tumor groups compared with normal samples regardless of CNV status." (PMID 37319315, 2023). "Its expression is predominantly neuronal, and though its role in cancer is not well defined, high levels of ADAR3 (ADARB2) correlate with improved prognosis in lower-grade gliomas (LGG), suggesting a possible tumor-suppressive function in specific contexts." (PMID 41300768, 2025). "Importantly, our validation using paired tumor and adjacent non-cancerous tissues confirmed this downregulation for ADARB2 but not for ADAR or ADARB1, suggesting that ADARB2 may represent the most robust biomarker candidate in this context." (PMID 41300768, 2025).
cancer (10 papers, 2019 to 2025). A tumor composed of atypical neoplastic, often pleomorphic cells that invade other tissues. "Among them, CDH1, ETNK2, ADARB2, and RAB40C are found to be aberrantly methylated in different cancers." (PMID 32961999, 2020). "This is crucial because the data obtained from the TCGA database indicate reduced methylation of the promoter of the gene encoding ADAR and increased methylation in the case of ADARB1 and ADARB2 in cancer tissue compared to non-cancerous tissue." (PMID 41300768, 2025).
metabolic disorders (3 papers, 2015 to 2020). "Adenosine deaminase, RNA specific B2 (ADARB2) related to longevity is associated with metabolic disorders like the abdominal circumference, body mass index, serum triglyceride level, and serum adiponectin level." (PMID 33329689, 2020).
ADARB2 also shares sentences with these, for which no sentence is quoted: amyotrophic lateral sclerosis (3 papers); astrocytoma (2); hepatocellular carcinoma (2); schizophrenia (2); Abdominal obesity (1); acute lymphoblastic leukemia (1); anaplastic astrocytoma (1); autism spectrum disorder (1); brain disorder (1); clear cell carcinoma (1); cognitive decline (1); colorectal cancer (1); dementia (1); dementia with Lewy bodies (1); diabetes (1); gastric cancer (1); hepatitis C (1); infection (1); Intellectual disability (1); leiomyoma (1); leiomyosarcoma (1); malignant melanoma (1); mesothelioma (1); neurological diseases (1); oligodendroglioma (1); papillary thyroid cancer (1); Parkinson (1); serous adenocarcinoma (1); squamous cell carcinoma (1); testis tumors (1).